TRPC6 (transient receptor potential cation channel subfamily C member 6)
Diseases named in the same sentence as TRPC6 in open-access papers (continued):
Sharing a sentence is not in itself a finding about the gene and the disease.
meningioma (1 paper, 2025). A generally slow growing tumor attached to the dura mater. "The results indicated that the expression of these four genes is causally stable in meningiomas (TRPC6: PIVW = 1.09×10−7; XBP1: PIVW = 4.28×10−11; TTC28: PIVW = 7.92×10−5; ODF3: PWald ratio = 7.94×10−8)." (PMID 40046334, 2025). "The odds ratios (ORs) of these genes were significantly high, indicating a positive causal relationship with meningiomas (TRPC6: ORIVW = 2.11; XBP1: ORIVW = 1.40; TTC28: ORIVW = 1.93 and ODF3: ORWald ratio = 4.76)." (PMID 40046334, 2025). "By extracting specific cells in which the four prioritized genes were expressed, we validated the high expression of XBP1, TTC28 and TRPC6 in meningioma tissues." (PMID 40046334, 2025). "The upregulation of TRPC6 in meningioma, particularly in tissue stem cells, suggests its involvement in maintaining stem cell-like characteristics, which are often associated with tumorigenesis and resistance to conventional therapies." (PMID 40046334, 2025). "The integration of bulk and single-cell RNA sequencing confirmed the upregulated expression of three of the genes (XBP1, TTC28 and TRPC6) in meningioma tissues, unravelling their cellular distribution and hinting at the tumour’s intrinsic heterogeneity." (PMID 40046334, 2025). "Therefore, co-development of targeted therapeutic agents for TRPC6 is important for meningiomas as well as renal disease." (PMID 40046334, 2025). "In this study, we performed SMR, colocalization and MR analyses using meningioma summary statistics from FinnGen r9 and eQTL data from eQTLGen, and identified XBP1, TTC28, TRPC6 and ODF3 as potential therapeutic gene targets for meningioma." (PMID 40046334, 2025). "In conclusion, the identification and validation of TRPC6, XBP1 and TTC28 as potential targets for meningioma therapy represent a significant advancement in our understanding of the disease and open new avenues for therapeutic interventions." (PMID 40046334, 2025). "We focused on differences in the expression of the four identified genes (XBP1, TTC28, TRPC6 and ODF3) between meningioma and normal brain tissues." (PMID 40046334, 2025).
nasal polyps (1 paper, 2021). "In line with an important role of TRP channels in immune cell dynamics, TRPC6-positive cells correlated positively with the number of eosinophils in histological specimens from nasal tissue in patients with eosinophilic chronic rhinosinusitis with nasal polyps." (PMID 34359824, 2021).
neuropathic pain (1 paper, 2020). Chronic pain caused by damage to nerve fibers. "Based on the previous in vitro study of TRPC6, we tested the efficacy of LA on mechanical hypersensitivity and cold allodynia, another modality of neuropathic pain, in a well-established neuropathic pain model, spared nerve injury (SNI)." (PMID 32299452, 2020).
neuropathy (1 paper, 2020). A disorder affecting the nervous system that manifests with pain, tingling, numbness, and/or muscle weakness. "Hence, understanding the detailed involvement of TRPC6 and HMGB1 in painful neuropathy would presumably reveal possibilities for therapeutic interventions for this devastating condition." (PMID 32019145, 2020).
Obesity (1 paper, 2021). Accumulation of substantial excess body fat. "Findings include missense variants in established drug targets for sleep disorders (HCRTR1, HCRTR2), genes with roles in arousal (TRPC6, PNOC), and genes suggesting an obesity-hypersomnolence pathway (PNOC, PATJ)." (PMID 33568662, 2021). "We identify 123 loci of which 61 replicate in the 23andMe research cohort, including variants in established drug targets for sleep disorders (HCRTR1, HCRTR2), genes with roles in arousal (TRPC6, PNOC), and genes suggesting an obesity-hypersomnolence pathway (PNOC, PATJ)." (PMID 33568662, 2021).
osteoporosis (1 paper, 2024). A condition of reduced bone mass, with decreased cortical thickness and a decrease in the number and size of the trabeculae of cancellous bone (but normal chemical composition), resulting in increased fracture incidence. "TRPC3 and TRPC6 are associated with osteoporosis, with TRPC3 promoting osteoclast differentiation and bone resorption in TRPC6-deficient phenotypes." (PMID 39170742, 2024).
periodontitis (1 paper, 2023). An acute or chronic inflammatory process that affects the tissues that surround and support the teeth. "This study evaluated the expression of TRPC3 and TRPC6 in periodontal tissue during periodontitis induction." (PMID 37653550, 2023). "The expression of TRPC3 and TRPC6 was investigated in mice periodontal tissue during a 28-day periodontitis induction period." (PMID 37653550, 2023). "Based on the results of previous studies and the expression of TRPC channels during osteoblast differentiation of PDL cells in this study, we focused on the expression of TRPC3 and TRPC6 during periodontitis progression, which was evaluated by immunohistochemical staining." (PMID 37653550, 2023). "Although a previous study showed that the application of mechanical force induced TRPC6 activation in the orthodontic tooth movement model, this study is the first to observe TRPC3 and TRPC6 expression in the periodontitis model." (PMID 37653550, 2023). "Experiments using TRPC3 and TRPC6 knockout animal models or TRPC3 and TRPC6 modulating drugs should be performed to determine how increased TRPC3 and TRPC6 expression is related to the progression of periodontitis." (PMID 37653550, 2023). "In ligature-induced periodontitis mice, the alveolar bone and osteoid areas, the osteoclast number, and the expression of Runx2, OCN, TRPC3, and TRPC6 was evaluated by H&E staining, TRAP staining, and immunohistochemistry, respectively." (PMID 37653550, 2023). "The TRPC6 expression of both the PDL area and the osteoblasts in the periodontitis group was consistently higher than that of the control group." (PMID 37653550, 2023). "Also, TRPC6 expression increased in both the PDL area and osteoblasts in the periodontal tissue of mice with periodontitis." (PMID 37653550, 2023). "In the future, changes in periodontal tissue should be observed by inducing periodontitis in TRPC3 and TRPC6 knockout animal models or by using TRPC3 and TRPC6 modulating drugs in a periodontitis animal model to clarify the functional role of TRPC3 and TRPC6 in periodontitis." (PMID 37653550, 2023). "This study observed an increase in the expression of TRPC3 and TRPC6 in PDL cells that were differentiating into osteoblasts and periodontitis-induced tissue but had a limitation in that the role of TRPC3 and TRPC6 in periodontitis could not be identified." (PMID 37653550, 2023).
peripheral arterial disease (1 paper, 2023). A disorder of the arteries supplying the upper and lower extremity and the visceral organs. "(iii) The reduced eNOS expression in hypercholesterolemic condition will increase the risk of peripheral arterial disease by preventing NO‐dependent phosphorylation of TRPC6." (PMID 36068079, 2023). "Cilostazol, a clinically approved drug for peripheral arterial disease, facilitates blood flow recovery by inactivating TRPC6 via phosphorylation at Thr69 in VSMCs." (PMID 36068079, 2023). "In TRPC6(−/−) mice, treatment with cilostazol had no additive effect on peripheral blood flow recovery after hindlimb ischaemia compared to vehicle treatment, strongly suggesting the involvement of TRPC6 in anti‐peripheral arterial disease effect by cilostazol." (PMID 36068079, 2023). "Suppression of TRPC6 could promote stabilization rather than formation of capillaries, which is consistent with the current idea that post‐angiogenic vessel maturation is more critical than angiogenesis for the improvement of peripheral arterial disease." (PMID 36068079, 2023).
primary hyperparathyroidism (1 paper, 2024). Hyperfunction of the parathyroid glands resulting in the overproduction of parathyroid hormone. "Surgery samples from patients with healthy parathyroid glands and from patients suffering from primary hyperparathyroidism (pHPT) were investigated by immunohistochemistry using knockout-validated antibodies against TRPC3 and TRPC6." (PMID 38673977, 2024).
Proteinuria (1 paper, 2022). Increased levels of protein in the urine. "In addition, it has been confirmed by patch-clamp electrophysiology that the current of TRPC6 was significantly increased, leading to Ca2+ overload in podocytes, resulting in cell damage in proteinuria disease." (PMID 35991898, 2022).
psoriasis plaques (1 paper, 2011). "Our findings of a diminished TRPC1-, TRPC4- and TRPC6-channel expression were confirmed by immunohistological stainings of punch biopsies from psoriasis plaques." (PMID 21364982, 2011).
Right ventricular hypertrophy (1 paper, 2017). In this case the right ventricle is more muscular than normal, causing a characteristic boot-shaped (coeur-en-sabot) appearance as seen on anterior- posterior chest x-rays. "Interestingly, in mice deficient for both TRPC1 and TRPC6, chronic hypoxia-induced changes in pulmonary arterial pressure, right ventricular hypertrophy, and pulmonary vascular remodeling are even more inhibited compared to those in mice with a deficiency for a single gene." (PMID 28670316, 2017). "Chronic treatment of rats exposed to 10% O2 for 21 days with sildenafil showed a decreased right ventricular pressure and right ventricular hypertrophy, which is related to decreased TRPC6 mRNA and protein expression in pulmonary arteries." (PMID 28670316, 2017).
type 2 diabetic nephropathy (1 paper, 2021). "Our results suggest that tacrolimus protects podocytes during the progression of type 2 diabetic nephropathy, possibly ameliorating podocyte apoptosis by downregulating the expression of TRPC6." (PMID 34095318, 2021).
urinary tract obstruction (1 paper, 2022). Blockage of the normal flow of contents of the urinary tract. "Based on studies in knockout mice, there is evidence that TRPC6 inhibition may be useful to reduce tubulointerstitial fibrosis, especially if it is caused by urinary tract obstruction, and, importantly, these conclusions are supported by pharmacological data." (PMID 36421724, 2022).
Ventricular arrhythmia (1 paper, 2014). "Interestingly, olmesartan decreased the increased expression of TRPC 6 in Gαq-TG mouse hearts in this study, suggesting that AT1 receptor activation contributes to an increase in TRPC6 expression, leading to ventricular arrhythmia induction." (PMID 25171374, 2014).
ZIKV infection (1 paper, 2024). "Conversely, no significant alterations were observed in the expression of TRPC1, TRPC3, TRPC5, or TRPC6 upon ZIKV infection." (PMID 39009885, 2024).
kidney diseases (53 papers, 2009 to 2025). "TRPC6 dysfunction, resulting from gene mutations or upregulation of its expression, is best understood in the context of pulmonary and renal diseases." (PMID 41118703, 2025). "TRPC6 channels are involved in smooth muscle function in vasculatures, and TRPC6 mutations have been linked to human kidney diseases." (PMID 37765099, 2023). "The available studies at least suggest that gain-of-function TRPC6 mutations that produce later onset nephrosis in humans tend to produce less severe kidney disease in mice." (PMID 36421724, 2022). "TRPC6 activation in podocytes causes required proteinuria kidney diseases and mediates Ang II-induced podocyte injury." (PMID 35490782, 2022). "Among them, TRPC6, which forms a signal transduction complex with nephrin and podocin on podocytes, is critical to podocyte injury susceptibility in kidney diseases." (PMID 36257404, 2022). "As with other kidney disease models that we examined, protein overload in wild-type rats was associated with a marked increase in the net abundance of TRPC6 and TRPC3 in renal cortex." (PMID 35805070, 2022). "TRPC6 channels have been implicated in the pathogenesis of kidney diseases, especially in familial nephrosis associated with mutations in the TRPC6 gene." (PMID 33918778, 2021). "Mutations in TRPC6 (e.g., P112Q, R895C, and E897K) have been proven to play a major role in podocyte depletion during renal disease, especially FSGS and SRNS." (PMID 31281825, 2019). "Canonical transient receptor potential‐6 (TRPC6) channels have been implicated in the progression of several forms of kidney disease." (PMID 32123821, 2019). "The effect of GOF mutations of TRPC6 in the pathophysiology of human kidney diseases has been well documented by several independent groups." (PMID 29736621, 2018). "It has been reported that overexpression of TRPC6 in podocytes was sufficient to cause a kidney disease consistent with focal and segmental glomerulosclerosis." (PMID 28400714, 2017). "The peak signal occurs within TRPC6, which encodes a cation channel subunit mutated in hereditary renal disease." (PMID 27560520, 2016). "Taking all our results together, we conclude that podocyte overexpression of wild type Trpc6, as well as both mutated forms analyzed, is sufficient to cause a kidney disease consistent with FSGS." (PMID 20877463, 2010). "We conclude that overexpression of Trpc6 (wild type or mutated) in podocytes is sufficient to cause a kidney disease consistent with FSGS." (PMID 20877463, 2010). "Indeed, as noted, several studies indicate that complete loss of TRPC6 can be protective in a variety of kidney disease models." (PMID 37615749, 2023). "Gain of function of TRPC6 mutations in podocytes resulted in renal diseases." (PMID 35490782, 2022). "Mutations in proteins that are specific for podocyte development and function, including α-actinin-4, nephrin, podocin, CD2AP, and TRPC6, lead to renal disease that is caused by the rearrangement of the actin cytoskeleton and the disruption of the filtration barrier." (PMID 31118506, 2019). "However, the manipulations that were used to produce FSGS-like lesions in those studies constrain conclusions that can be drawn since the kidney disease was transient and mild, even in Trpc6+/+ controls or entailed genetic manipulations that cause artificial sustained TRPC6 activation." (PMID 29785489, 2018). "This obvious diversity in the molecular phenotypes of these mutants has become a perplexing enigma for understanding the mechanisms of TRPC6 in kidney disease." (PMID 37615749, 2023). "TRPC6-mediated signalling has been shown to be involved in the pathogenesis of these acquired forms of kidney diseases as well." (PMID 38003608, 2023). "In the present study, we examine the effect of TRPC6 inactivation in a four-week albumin overload model of kidney disease in Sprague Dawley rats." (PMID 35805070, 2022).
kidney diseases (continued). "If TRPC6 channels are therapeutically useful targets, then the inhibition or inactivation of TRPC6 channels should reduce various indices of kidney disease in animal models in which glomerular function is altered." (PMID 35805070, 2022). "The purpose of this review is to summarize the evidence to date on the potential of TRPC6 as a drug target, with a particular emphasis on the effects of TRPC6 knockouts in animal models of kidney disease." (PMID 36421724, 2022). "There is often an increase in TRPC6 abundance in human kidney diseases and in kidney disease models in mice and rats, and in podocytes there are disease conditions that induce a marked increase in TRPC6 currents and altered gating properties." (PMID 36421724, 2022). "Studies using TRPC6 knockout animals support continuing drug discovery efforts that target TRPC6 channels directly or indirectly for therapy of kidney diseases." (PMID 36421724, 2022). "One ion channel that has received particular attention in the context of kidney disease is the canonical transient receptor potential-6 channel (TRPC6)." (PMID 36421724, 2022). "It has also been shown that activation of TRPC6 can lead to an increase in its own transcription in podocytes, and TRPC6 can therefore function as part of a positive feedback pathway that drives the progression of kidney disease." (PMID 36421724, 2022). "As a result, TRPC6 has become a critical target of therapeutic agents to prevent and treat various kidney diseases." (PMID 34483931, 2021). "The abnormal expression of TRPC6 in podocyte is closely related to the occurrence of proteinuria in a variety of kidney diseases." (PMID 31998809, 2020). "On the basis of these findings, TRPC6 has become an important target for the development of therapeutic agents to treat diverse kidney diseases." (PMID 31877991, 2019). "Future research will focus on the mechanisms by which TRPC6 specific affects the pathophysiology of the renal disease." (PMID 29619864, 2018). "TRPC6-mediated calcium influx plays an important role in renal diseases; therefore, the difference in TRPC6 function after treatment with pharmacological inhibitors or siRNA knockdown was also investigated in this study." (PMID 25393730, 2014). "Consistent with the phenotype observed in patients with kidney disease, our Trpc6 transgenic mice presented albuminuria in adult male mice with variable penetrance observed in the analyzed transgenic lines." (PMID 20877463, 2010). "Among the TRP family, certain members, such as transient receptor potential canonical 1 (TRPC1), transient receptor potential canonical 6 (TRPC6), and transient receptor potential melastatin 2 (TRPM2), have been implicated in obesity, oxidative stress, and kidney diseases." (PMID 41009007, 2025). "In summary, TRPC6 could play an important role in glomerular inflammation and tubulointerstitial fibrosis in several types of kidney diseases that are characterized by immune cell infiltration." (PMID 38003608, 2023). "Collectively, these data support TRPC6 inhibition as a therapeutic strategy for several forms of kidney disease, although the nature and extent of the protective effect may depend on the actual disease model, the species, and the genetic background." (PMID 35805070, 2022). "Our results improve the understanding of the role of TRPC6 role in kidney diseases." (PMID 35194063, 2022). "It has been argued that enhanced mechanical activation of TRPC6 in certain kidney disease states may be a factor that contributes to renal pathology, as will be discussed further below." (PMID 36421724, 2022). "However, the effects of TRPC6 knockout have also been studied in diabetic rats, which typically show more severe renal disease." (PMID 36421724, 2022). "Given the crucial role of miRNAs in the progression of kidney diseases, we hypothesized that specific miRNAs might mediate dysregulated TRPC6 expression." (PMID 36257404, 2022).